IL1B (interleukin 1 beta)
Diseases named in the same sentence as IL1B in open-access papers (continued):
Sharing a sentence is not in itself a finding about the gene and the disease.
ischemia (continued). "In the hippocampus, pre-ischemia melatonin administration showed a significantly higher reduction in IL-1β levels, as compared to the post-ischemia treatment (p < 0.01)." (PMID 30029514, 2018). "In summary, systemic infusions of anti-IL-1β mAb after ischemia result in anti-IL-1β mAb uptake into the brain, reduce I/R-related increases in the IL-1β protein, and promote increases in non-specific BBB permeability across brain regions in the fetus." (PMID 29875342, 2018). "Treatment with IL-1β, at the same concentration as used herein in mixed cultures (10 ng/mL), protected organotypic hippocampal cultures from simulated ischemia, although hypoxic neuronal damage was enhanced." (PMID 30044427, 2018). "Under conditions with compromised Glu uptake (like ischemia), increased Il-1β has been shown to enhance the expression/activity of system xc- only on astrocytes, which contributes to increased excitotoxicity." (PMID 29045497, 2017). "Because the cytokines, TNF-α and IL-1β are the most important pro-inflammatory mediators after the onset of ischemia." (PMID 27716383, 2016). "Recently, some researchers have found that in the fetus, the anti-IL-1β mAb which be taken up by brain in ischemia-reperfusion injury, can then attenuates ischemia-reperfusion related fetal BBB dysfunction." (PMID 26925269, 2016). "Paeonol exerts anti-infarct effect mainly by inhibiting microglial activation and IL-1β expression in the ischemic cortex in ischemia/reperfusion- (I/R-) injured rats." (PMID 27703487, 2016). "The LXW7 group exhibited lower expressions of TNF-α and IL-1β, compared to the ischemia group (P<0.05)." (PMID 27533766, 2016). "The expressions of the TNF-α and IL-1β proteins were significantly higher in the ischemia group, compared to the sham-operated group (P<0.05)." (PMID 27533766, 2016). "Compared with the ischemia group, the IL-1β and IL-6 serum levels were significantly reduced in the ischemia + low-, medium- and high-dose NaHS groups; in the ischemia + medium- and high-dose NaHS groups the TNF-α level in the serum was significantly reduced." (PMID 25667680, 2015). "Compared with the sham surgery group, the TNF-α, IL-1β and IL-6 serum levels in the rats were significantly elevated in the ischemia group (P<0.01)." (PMID 25667680, 2015). "IL1β is also highly concentrated in cerebrovascular endothelium, and increase after excito-toxic injury, LPS challenge, mechanical damage, and ischemia." (PMID 25592846, 2015). "In the ischemia + PPG group, the serum levels of TNF-α, IL-1β and IL-6 were significantly increased compared with those in the ischemia group (P<0.05 or P<0.01)." (PMID 25667680, 2015). "The induction of cerebral ischemia increased IL-1β mRNA expression levels significantly at 4 and 24 h following ischemia in the left ischemic hemispheres in the hypoxia group compared with those in the control (P=0.002 for 4 and 24 h)." (PMID 24520277, 2014). "Our findings revealed that DHI treatment significantly suppressed the expression of proinflammatory cytokines TNF-α and IL-1β levels after ischemia." (PMID 24707308, 2014). "In the present study, we demonstrated that the ischemia-induced up-regulation of iNOS, IL-1β, IL-6 and TNF-α was inhibited by treatment with GL." (PMID 24594628, 2014). "The results indicated that levels of IL-1β were increased about 4.1-fold in ischemia-treated rats compared with the sham-operated group (MCAO, 144.3±7.8 pg·ml−1 versus sham, 28.01±3.2 pg·ml−1, p<0.001; n = 6)." (PMID 24979385, 2014). "EPC numbers in the ischemic muscle were also significantly reduced in IL-1β−/− mice, indicating a crucial role for IL-1β in ischemia-induced EPC mobilization and homing." (PMID 24385987, 2013). "Other studies confirmed also that inflammatory mediators, such as IL-1β and TNFα, are important contributors to CNS neural tissue damage induced by ischemia." (PMID 24324296, 2013).
ischemia (continued). "A growing body of evidence indicates that the inflammatory response, associated with pro-inflammatory cytokines IL-1β, TNF-α and chemotactic cytokine MCP-1, plays a major role in renal dysfunction following ischemia and reperfusion." (PMID 23759023, 2013). "In response to load, IL-1β decreased only in young whereas it remained low in aged skin, suggesting a decreased inflammatory response to loading and ischemia." (PMID 23967056, 2013). "We further examined the expression of HIF-1α, TNF-α and IL1-β after ischemia and when treated with Melissa in the ischemic rat brain." (PMID 23351182, 2012). "It was previously shown that IL-1β expression is also up-regulated in a rodent model of experimental testicular ischemia-reperfusion." (PMID 21298060, 2011). "In fact it is thought that the relative production of IL-1ra or IL-1β in response to either mild or severe ischemia appears to be quite important in determining outcome." (PMID 22114930, 2011). "Stress-induced proinflammatory cytokines, particularly TNF-α and IL-1β synthesized and released in response to the stress of global ischemia accompanying CA, play a pivotal role in development of postresuscitation ventricular dysfunction." (PMID 22011328, 2011). "A number of studies have demonstrated that administration of IL-1β concurrent with experimental ischemia is capable of exacerbating injury." (PMID 18302763, 2008). "Moreover, activation of inflammasome-mediated IL-1β secretion aggravates intestinal ischemia-reperfusion injury by inhibiting autophagy in mice, whereas knockdown of NLRP3 reverses these effects." (PMID 40362581, 2025). "Moreover, the IL-1β gene expression in the EP-treated ischemia group decreased compared to the Ischemia group (P<0.05)." (PMID 40809171, 2025). "Importantly, PCL-Gd/CA nanoparticles also decreased HIF-1α and IL-1β levels in OHCs exposed to experimental ischemia/reperfusion." (PMID 39786699, 2025). "The expression of CD4+ using the immunohistochemistry (IHC) method and gene expression of IL-1β using the Real-time PCR in the ischemic penumbra of the male rat’s brain cortex were determined, and infarct volume was determined 24 hr after ischemia using TTC staining." (PMID 40809171, 2025). "Also, E/P administration reduced infarct volume and CD4+ and gene expression of IL-1β compared to the Ischemia group." (PMID 40809171, 2025). "The IL-1β gene expression in the ischemic penumbra in the EP-treated ischemia group decreased." (PMID 40809171, 2025). "Moreover, macrophage IL-1β was absolutely required for postdevelopmental arteriogenesis in the hindlimb ischemia model, likely secondary to IL-1β-driven proangiogenic VEGF-A expression." (PMID 40299401, 2025). "Treatment with an anti-IL-1β antibody before the onset of ischemia reduces damage." (PMID 39333859, 2024). "IL-1β increased neuron excitability, which may contribute to seizures, multiple sclerosis, and ischemia." (PMID 38438808, 2024). "Furthermore, pathway analysis indicated that a combination of P2Y1R-ANT and MCM suppressed inflammatory pathways, including the MAPK/NF-κB/TNF-α or IL-1β signaling in reactive astrocytes after ischemia." (PMID 37676390, 2024). "In addition, the TM extract and its bioactive ingredients exert anti-inflammatory effects by downregulating a variety of proinflammatory mediators, such as TNF-α, IL-1β, and nitric oxide, in various models of ischemia-induced injury." (PMID 39391701, 2024). "Moreover, genetic deletion or pharmacological inhibition of S100A8/A9 can inhibit the TLR4/NLRP3/IL-1β pathway, suppressing ischemia-induced granulopoiesis and improving cardiac dysfunction." (PMID 36768433, 2023). "IL1B is a key player in the pathogenesis of brain damage after ischemia." (PMID 36803375, 2023). "Moreover, two other experimental studies on a rat model showed that the IL-1β level was increased in injured renal tissues after 30 minutes of ischemia, followed by 2 hours of reperfusion." (PMID 37305825, 2023).
ischemia (continued). "In support of the key role of mechanosensory Panx1 signaling in the retina, recent reports showed its pivotal role in both acute ischemia-induced and glaucomatous degeneration, where its activity strongly correlated with the induction of the inflammasome and production of IL-1β." (PMID 37998361, 2023). "Cytokines such as IL-1-β and IL-6 from blood vessel endothelial cells and phagocytic mononuclear cells are rapidly synthesized and released into circulation during ischemia and IR, along with increased oxidative stress and inflammation during IR blood flow deceleration and oxygen restriction." (PMID 37132757, 2023). "In addition, at both late time points, 3 and 7 days after ischemia induction, a high number of IL-1β+ signals were noted in ischemia in contrast to controls (3 days: p < 0.001, 7 days: p < 0.001)." (PMID 32833183, 2021). "This theory is supported by a recent study showing that inhibition of IL-1β starting at an extended time-point after reperfusion results in improved systolic function in an ischemia-reperfusion rat model, with already established cardiac dilation and dysfunction." (PMID 34768376, 2021). "To investigate whether IL-1β and IL-23 are also upregulated following ischemia, we investigated their expression in microglia and macrophages sorted from ischemic hemispheres." (PMID 34772416, 2021). "Likewise, the expression of the IL‐1β precursor was significantly elevated on day three post‐ischemia by WB." (PMID 32343048, 2020). "Furthermore, IL-1β is known as the major cytokine contributing to cardiac ischemia reperfusion injury due to activation through the inflammasome." (PMID 33291425, 2020). "Moreover, some studies using MCP-1-deficient mice indicate that MCP-1 signaling-mediated IL-1β upregulation influences BBB disruption and aggravates ischemia-related neuronal damage." (PMID 32264971, 2020). "The rapid release of TNFα, IL‐6, IL‐1β, and interferon γ (IFNγ) by microglia upon ischemia induces the upregulation of adhesion molecules such P‐Selectin, E‐Selectin, intercellular adhesion molecule (ICAM), and vascular cell adhesion molecule (VCAM) by endothelial cells." (PMID 33058417, 2020). "In addition, it was shown that exposure to bacterial lipopolysaccharide (LPS) before the induction of ischemia can train microglia to produce higher amounts of IL‐1β." (PMID 33058417, 2020). "For instance, it has been reported IL-1β acts as a cardio-depressant cytokine where single or multiple injections of IL-1β causes systolic dysfunction and reduces LV contractility reserve in healthy mice and human subjects in the absence of ischemia." (PMID 31319469, 2019). "In addition, we have recently demonstrated that the anti-IL-1β mAb attenuates short-term histopathological I/R-related tissue injury, reduces ischemia-related increases in apoptosis, and reduces I/R-related increases in caspase-3 activity in the fetal brain." (PMID 29875342, 2018). "Consequently, systemic infusions of anti-IL-1β mAb also attenuate short-term I/R-related parenchymal brain injury after ischemia in the fetus." (PMID 29875342, 2018). "Furthermore, the neurologic score was consistent with the mRNA transcription levels of NLRP3, IL-1β, and caspase-1 in the ischemia core." (PMID 29853850, 2018). "Related work has shown that the infusion of IL-1β neutralizing antibodies could reduce ischemia-related increases in BBB permeability." (PMID 29334965, 2018). "IL-1, and in particular, IL-1β plays an important role in brain injury during ischemia." (PMID 28115020, 2017). "Moreover, Ginkgo biloba treated I/R group showed significantly decreased plasma levels of IL1-β and TNF-α compared to I/R group and caused improved histological disruption of spermatogenesis observed in ischemia only and I/R groups." (PMID 28101298, 2016).
ischemia (continued). "The present study confirmed that IL-1β and TNF-α were induced by ischemia; however, IL-1β was downregulated in the serum of the GLGZD-2 group following treatment (P<0.05) and TNF-α was downregulated in the serum of the GLGZD-1 group following treatment (P<0.05)." (PMID 25815894, 2015). "And previous studies have already proved that the injection of antagonists of TNF-α and IL-1β could relieve the ischemia injury." (PMID 24707308, 2014). "Additionally, the therapeutic reagents that diminish either TNF-α or IL-1β production have been found in other models of neurological diseases, including ischemia, traumatic brain injury and SCI." (PMID 25014398, 2014). "IL-1β and iNOS were upregulated at a slower rate and peaked 72 hours after onset of ischemia." (PMID 21171972, 2010). "TNF-α and IL-1β, as the pro-inflammatory cytokines released under different stimulation of many cell types, play a critical role in glia activation and infiltration of inflammatory cells, further aggravating brain edema and enlarging the damage to ischemia nerve cell injury after CIRI." (PMID 33927611, 2021). "In addition, overproduction of IL-1β could promote ROS production, resulting in oxidative damage after ischemia." (PMID 33735403, 2021). "Lytic forms of cell death seemed to augment systemic auto-inflammation in an FMF model, and acute tissue injuries in ischemia and transplantation models through the excess production of IL-1β and DAMPs, which could mediate pathology by the activation of innate immune cells." (PMID 34548542, 2021). "In the vehicle + TFI group, IL-1β immunoreactivity in the pyramidal cells was dramatically increased (189.3% of the sham group) at 2 days post-ischemia, but, at 5 days post-ischemia, IL-1β immunoreactivity in the pyramidal cells was hardly shown (27.9% of the sham group) due to their death." (PMID 34361744, 2021). "Furthermore, also isoform-specific IL-1 inhibition by mean of anti-IL-1β and anti-IL-1α neutralizing antibodies was shown to reduce inflammasome activation and preserve left-ventricular systolic function, even if administered after ischemia." (PMID 33770265, 2021). "Moreover, as per our findings, ischemia led to an increase in the HDAC9 expression in the brain of wild type mice, while the loss of HDAC9 was observed to suppress the release of IL-1β, IL-6, IL-18, and TNF-α in the mouse cortex, hippocampus, and hypothalamus after I/R injury." (PMID 33584204, 2020). "Expression of the cytokines Tnf-α and Il-1β and of the gliosis marker Glast, Vim, Gs and Gfap were evaluated 24 hours after ischemia by means of qRT-PCR to determine whether inflammation or an altered gliotic response is involved in FXN-mediated neuroprotection." (PMID 29555919, 2018). "Furthermore, endogenous zinc release was induced by cerebral ischaemia–reperfusion, resulting in increased expression of IL-1β, IL-6, TNFα, and the microglial M1 surface marker CD16/32, without hippocampal neuronal cell loss, in addition to impairments in object recognition memory." (PMID 28240322, 2017). "The level of IL-1β was also very low at baseline (0.71 ± 0.1 pg/mg protein, sham group), slightly increased 2 h after the hypoxia-ischemia insult (3.15 ± 0.52 pg/mg protein, HI group), and markedly elevated 6 h after the hypoxia-ischemia insult (25.97 ± 3.89 pg/mg protein, HI group)." (PMID 26273140, 2015). "However, it is thought that transient ischemia-induced activation of NF-κB/p65 via toll like receptor 4 or 2 in glial cells would exert secondary injury to neurons by producing neuro-toxic cytokins such as TNFα and IL-1β." (PMID 24800741, 2014). "Following MCAO, the expression of IL-1β and CD4+ increased in the penumbra region of the cerebral cortex, and treatment with estrogen and progesterone modulated the adverse effects of ischemia on the cerebral cortex and decreased infarct size." (PMID 40809171, 2025).
ischemia (continued). "Exosomes derived from MSCs can ameliorate inflammation after acute ischemia or ischemia–reperfusion injury by modulating anti-inflammatory molecules (IL-4 and IL-10) and pro-inflammatory cytokines (IL-6, TNF-α, and IL-1β), and inhibiting microglia activation." (PMID 40771978, 2025). "Carthamus tinctorius L. [Asteraceae; Carthami flos] reduces cerebral infarction and neurological deficits in ischemia-reperfusion injury and cerebral infarction models by mitigating free radicals and pro-inflammatory cytokines, including TNF-α and IL-1β." (PMID 41438511, 2025). "Colchicine mitigates inflammation triggered by ischemia by indirectly inhibiting NLRP3 oligomerization, which reduces the production of IL-1β and IL-18." (PMID 40149903, 2025). "During the acute phase of ischemia, microglia are activated to secrete cytokines such as TNF-α, IL-1β, and IL-6, which further exacerbate the destruction of BBB." (PMID 40260076, 2025). "It regulates the expression of proteins such as IL1B (interleukin-1 beta) and CXCL2 (C-X-C motif chemokine ligand 2) involved in the inflammatory process and the development of tissue damage after ischemia." (PMID 38956704, 2024). "In a mouse model in which ischemia was pharmacologically induced, it was observed that TREM-1 promotes the production of IL-1β, IL-18, IL-6, CXCL-2, MCP-1, and CXCL-1 in microglia." (PMID 39062850, 2024). "IL-1β, TNF-α, and NFκB-p65 mRNA expression levels were significantly increased in the ischemia and I/R groups in comparison to the healthy group (P<0.05)." (PMID 37886007, 2023). "Activated microglia serve a dual role during ischemia, releasing pro-inflammatory cytokines (such as TNF-α and IL-1β) that can aggravate ischemic injury, whilst promoting the release of anti-inflammatory cytokines (such as IL-10) to reduce ischemic injury." (PMID 36725745, 2023). "Cytokines, namely, IL‐1β, TNF‐α, IL‐6 and IFN‐γ, rise 24 h post ischemia in a tMCAO model, and reducing the concentrations of these cytokines are highly advantageous to IS treatment." (PMID 37132060, 2023). "The neuroprotective mechanisms of 6 mg/kg purpurin were evaluated in terms of anti-inflammatory responses in the hippocampus using an ELISA assay for IL-1β, IL-6, and TNF-α 6 h after ischemia." (PMID 35094304, 2022). "IL-1β, IL-6, and TNF-α levels were significantly decreased 4 days in the hippocampus after ischemia compared to 6 h post-ischemic group, respectively." (PMID 35094304, 2022). "In primary rat cerebellar neuronal-glial cell cultures affected by ischemia, propolis significantly protected the cultures from hypoxia-induced elevation of TNF-α, IL-1β and IL-6." (PMID 36500579, 2022). "In transient global ischemia in OVX rats, G1 inhibited inflammation decreasing the expression of NLRP3-ASC-caspase 1 inflammasome and IL-1β as well as NF-κB signaling." (PMID 34830207, 2021). "The inflammatory markers, IL‐1β and TGF‐β1 promote extracellular matrix remodeling and cardiac collagen expression and aggravate VA induced by ischemia." (PMID 33270361, 2021). "In the present study, transient ischemia significantly increased lipid peroxidation and pro-inflammatory cytokines IL-1β, IL-6, and TNF-α in the hippocampus 6 h after ischemia." (PMID 34203930, 2021). "Transient forebrain ischemia significantly increased IL-1β and TNF-α levels in hippocampal homogenates, and cuprizone treatment aggravated the increase in IL-1β and TNF-α in the hippocampus after ischemia." (PMID 32531881, 2020). "We measured the expression of proinflammatory cytokines (IL-1β, IL-6, and TNF-α) in the ischemia penumbra 24 h after reperfusion." (PMID 32917229, 2020). "We found that CSO treatment significantly inhibited the hyperactivation of microglia and astrocytes and significantly decreased the expression levels of proinflammatory cytokines (IL-1β, IL-6, and TNF-α) in the ischemia penumbra after MCAO-R injury." (PMID 32917229, 2020).